MIR5701-3 (microRNA 5701-3)
Synonyms: hsa-mir-5701-3
Gene: MicroRNA gene on chromosome 15 (21,951,242 to 21,951,323, forward strand). Ensembl gene ENSG00000264902.
Homologues: Paralogues in human: MIR5701-1 (100% identical), MIR5701-2 (100% identical).